ROCK1 (Rho associated coiled-coil containing protein kinase 1)
Diseases named in the same sentence as ROCK1 in open-access papers (continued):
Sharing a sentence is not in itself a finding about the gene and the disease.
leukemia (15 papers, 2013 to 2024). A malignant (clonal) hematologic disorder, involving hematopoietic stem cells and characterized by the presence of primitive or atypical myeloid or lymphoid cells in the bone marrow and the blood. "Our in vivo study also showed that the MC-3129-mediated inhibition of the tumor growth in a mouse leukemia xenograft model is associated with the interruption of ROCK1/PTEN/PI3K/Akt signaling and apoptosis." (PMID 29844397, 2018). "An anti-apoptotic effect of ROCK1 has been reported in bladder cancer and leukemia, and it was demonstrated that ROCK1 can disrupt the apoptotic-signaling cascade through inhibitory binding to Erk1/2 kinase." (PMID 31557128, 2019). "Our results provide detailed information on the molecular mechanisms by which MC-3129 induces apoptosis in human leukemia cells (i.e., by activation of RhoA/ROCK1/PTEN and inactivation of PI3K/Akt)." (PMID 29844397, 2018). "Our results provide detailed information on the molecular mechanisms by which cerulenin induces apoptosis in human leukemia cells (i.e. by activation of ROCK1, inactivation of Akt, and activation of JNK)." (PMID 26967395, 2016). "In leukemia, ROCK1 bound to Erk1/2, and inhibiting ROCK released Erk1/2, consequently increasing apoptosis." (PMID 26725045, 2016). "Our previous study showed that ROCK1 activation plays a critical role in regulating cofilin mitochondrial translocation and apoptosis in leukemia cells." (PMID 25595902, 2015). "To further elucidate the mechanism of PTEN regulation by ROCK1, we examined the binding of PTEN and ROCK1 in response to AITC treatment in leukemia cells." (PMID 23895248, 2013). "Further study determined that HOTAIRM1 bound to the transcriptional inhibitory region of ARHGAP18 and repressed the expression of ARHGAP18, which led to the increase of RHOA/ROCK1 signaling pathway and promoted GC resistance through antiapoptosis of leukemia cells." (PMID 34262023, 2021). "However, a study using human leukemia cells showed that activation of the RhoA/ROCK1 pathway decreased p-ERK1/2 in the nucleus, and inhibition of RhoA/ROCK1 led to accumulation of n-p-ERK1/249." (PMID 26148871, 2015). "Taken together, these results demonstrate that ROCK1 plays a significant role in regulating the activation of PTEN in response to AITC treatment in leukemia cells, which probably contributes to dephosphorylation and mitochondrial translocation of cofilin and induction of apoptosis." (PMID 23895248, 2013). "Taken together, these results suggest that ROCK1 is an attractive potential therapeutic target for AML, and GSK269962A can effectively inhibit leukemia proliferation in vitro and in vivo." (PMID 36561342, 2022). "Stimulation of ROCK1 phosphorylates downstream MLC2 on Ser119, corresponding to actin and myosin changes that promote the acceleration of leukemia cell proliferation; this has been suggested to have consequences for myeloproliferative neoplasms (MPNs) and AML." (PMID 34638385, 2021). "As these findings suggested that ROCK1 could be a potential therapeutic target for AML, evaluating the anti-leukemia effect of ROCK1 inhibitor in preclinical models might be of potential value." (PMID 36561342, 2022). "In leukemia, HOTAIRM1 was considered to be unfavorable and it could activate RHOA/ROCK1 pathway to enhance glucocorticoid resistance by inhibiting ARHGAP18." (PMID 35087800, 2021). "Our study reveals a novel role for RhoA/ROCK1/PTEN/PI3K/Akt signaling in the regulation of mitochondrial translocation of cofilin and apoptosis and suggests MC-3129 as a potential drug for the treatment of human leukemia." (PMID 29844397, 2018). "ROCK1/2 inhibition improved survival and histological GVHD severity in mice and was synergistic with JAK1/2 inhibition, without compromising graft-versus-leukemia-effects." (PMID 38199985, 2024).
leukemia (continued). "However, the functional role of the ROCK1/Akt/JNK signaling pathway in the regulation of dephosphorylation and mitochondrial translocation of cofilin, which results in cerulenin-mediated mitochondrial injury and apoptosis in human leukemia cells, is not yet clear." (PMID 26967395, 2016).
diabetic nephropathy (14 papers, 2013 to 2026). "The recruitment of Drp1 is stimulated by Rho-associated coiled coil-containing protein kinase 1 (ROCK1), which has been implicated in promoting albuminuria, mesangial matrix expansion, and podocyte apoptosis in diabetic nephropathy in mice." (PMID 34248614, 2021). "The ROCK1 signalling pathway has been implicated in several diseases, such as diabetic nephropathy (DN) and DR, and in the diabetic milieu, high glucose levels can activate the ROCK1 pathway in vascular cells." (PMID 32297701, 2020). "Genetic models strongly support the pathogenic role of ROCK1 in diabetic nephropathy." (PMID 41311514, 2026). "As a downstream effector of TGF-β, Rock1 has been shown to induce EndMT in diabetic nephropathy by regulating cytoskeletal remodeling, mitochondrial fission, and apoptosis." (PMID 41535231, 2026). "The distinct pathological contributions of ROCK1 to diabetic nephropathy have been increasingly elucidated through research into its metabolic regulatory functions." (PMID 41311514, 2026). "In diabetic nephropathy, Drp1 was identified as a direct substrate for ROCK1, and ROCK1 was proved to mediate phosphorylation of Drp1 at Ser600." (PMID 35865967, 2022). "The lncRNA ZFAS1 regulates the proliferation, oxidative stress, fibrosis, and inflammation of high glucose-induced diabetic nephropathy through the miR-588/ROCK1 axis." (PMID 35090549, 2022). "Altogether, our data suggest that ZFAS1 regulates the proliferation, oxidative stress, fibrosis, and inflammation of high glucose-induced diabetic nephropathy through the miR-588/ROCK1 axis." (PMID 35090549, 2022). "ROCK1 is a potent regulator of mitochondrial dynamics in diabetic nephropathy and Drp1 is a direct substrate for ROCK1." (PMID 24834056, 2014). "The development of ROCK1-selective inhibitors remains an important unmet need that could provide valuable tools for targeting metabolic aspects of diabetic nephropathy." (PMID 41311514, 2026). "This comprehensive review consolidates current knowledge on the distinct pathophysiological roles of the ROCK isoforms, ROCK1 and ROCK2, in diabetic nephropathy, drawing on recent insights from both genetic and pharmacological studies." (PMID 41311514, 2026).
glioblastoma (14 papers, 2013 to 2025). The most malignant astrocytic tumor (WHO grade IV). "Since we observed a significant benefit from reducing ROCK1 levels both in human cells in culture and in intact C. elegans aggregation models, we measured its levels in T98G glioblastoma cells that overexpress either the APOE3 or APOE4 allele." (PMID 35890250, 2022). "These C. elegans results are similar to those observed in the human glioblastoma cell line, T98G, in which siRNA KD of ROCK1, AKT2, or PKA reduced total aggregate protein by 50–60%." (PMID 35890250, 2022). "Evodiamine can inhibit cell proliferation by inhibiting PI3K/Akt signal to induce apoptosis and activate MAPK in pleomorphic glioblastomas and effectively inhibit the protein expression of Rho, ROCK1, and ROCK2." (PMID 34925530, 2021). "In our present study, paeoniflorin suppressed HGF-mediated migration and invasion and actin cytoskeleton rearrangement of glioblastoma cells, and the mechanism involved c-Met/RhoA/ROCK1 signaling regulation." (PMID 30886866, 2019). "To further elucidate the role of phosphocofilin in glioblastoma cells we applied inhibitors for ROCK1/2 and LIMK1/2 to our model." (PMID 29724193, 2018). "Another group has developed 3D cultures for glioblastoma using polyethylene-glycol-based hydrogel to modulate matrix stiffness, and found that increasing matrix stiffness induced upregulation of ROCK1." (PMID 27203208, 2016). "ROCK1 and ROCK2 have been shown to play opposing roles in glioblastomas, where the knockdown of ROCK2 was seen to enhance proliferation whereas the inhibition of ROCK1 was seen to decrease the proliferation of glioblastoma cells." (PMID 31488179, 2019). "ShRNA was used to downregulate ROCK1 and ROCK2 expressions in the D54MG and 86HG39 glioblastoma cell lines, and the effects on cell migration, proliferation, substrate-dependent migration, and signaling pathways were compared." (PMID 24170433, 2014). "There are two ROCK isoforms: ROCK1, which is upregulated in glioblastoma tissue compared to normal brain tissue, and ROCK2, which is also expressed in normal brain tissue." (PMID 24170433, 2014). "After miR‐218 overexpression in glioblastoma cells, we observed a decrease in the expression levels of GBM oncogenes such as PIK3CA, ROCK1, LAMC1 and ICAM1." (PMID 35702951, 2022).
pulmonary fibrosis (14 papers, 2014 to 2025). Chronic progressive interstitial lung disorder characterized by the replacement of the lung tissue by connective tissue, leading to progressive dyspnea, respiratory failure, or right heart failure. "It has been reported that ROCK1 signaling pathway is associated with fibrotic lesions in various organs, such as pulmonary fibrosis, liver fibrosis, myocardial fibrosis, and renal fibrosis." (PMID 39229866, 2024). "They used a NOTCH1 inhibitor in a mouse model of pulmonary fibrosis, which successfully inhibited the PDGFRβ/Rho associated coiled-coil containing protein kinase 1 (ROCK1) pathway, inhibited the proliferation and differentiation of pericytes, and reduced the severity of fibrosis." (PMID 34776968, 2021). "Three proteins (mammalian target of rapamycin, mTOR; zinc finger E-box-binding homeobox 1, ZEB1; Rho-associated, coiled-coil containing protein kinase 1, ROCK1) may be related to pulmonary fibrosis." (PMID 25358403, 2014). "A previous study found that reduced expression of ROCK1 or ROCK2 was sufficient to protect mice from experimental pulmonary fibrosis." (PMID 37864185, 2023). "Previous research on murine ROCK-haploinsufficient models shows reduced ROCK1/2 expressions protections against bleomycin-induced lung fibrosis." (PMID 34204955, 2021). "In the study of lung diseases, NOX4/ROS can activate the RhoA/ROCK1 signal pathway, promote the migration of pulmonary fibroblasts and collagen synthesis, and aggravate pulmonary fibrosis." (PMID 34135982, 2021). "To substantiate the effect of the Notch1/PDGFRβ/ROCK1 axis on pericyte differentiation and pulmonary fibrosis, we generated a mouse pulmonary fibrosis model in which the Notch1 signaling pathway inhibitor DAPT was used as a treatment." (PMID 30902967, 2019). "As further substantiation, the administration of a Notch1 inhibitor in a mouse model of lung fibrosis inhibited the PDGFRβ/ROCK1 pathway, suppressed pericyte proliferation and differentiation, and alleviated the severity of fibrosis." (PMID 30902967, 2019). "The goals of this study were to investigate the role of the Notch1/PDGFRβ/ROCK1 signaling pathway in the pathogenesis of pulmonary fibrosis and to explore the possibility of treating fibrosis by targeting Notch1." (PMID 30902967, 2019). "Lung tissues from patients with pulmonary fibrosis were examined for the expression of Notch1/PDGFRβ/ROCK1 using RT-qPCR, western blotting, and immunostaining." (PMID 30902967, 2019). "We assessed the clinical significance of mTOR, ZEB1, and ROCK1 expression in human pulmonary fibrosis of usual interstitial pneumonia (UIP) pattern." (PMID 25358403, 2014). "This study was performed to identify the clinical significance of mTOR, ZEB1, and ROCK1 expression in the lung tissues of idiopathic pulmonary fibrosis and UIP pattern connective tissue disease related interstitial lung disease (CTD-ILD) patients." (PMID 25358403, 2014). "The expression of mTOR, ZEB1, and ROCK1 was increased in most of the lung tissues of pulmonary fibrosis patients." (PMID 25358403, 2014). "We first demonstrated that mTOR, ZEB1 and ROCK1 was expressed in hyperplastic alveolar epithelial cells of human pulmonary fibrosis lungs." (PMID 25358403, 2014). "This was the first study to evaluate mTOR, ZEB1, and ROCK1 expression in the lung tissues of pulmonary fibrosis patients." (PMID 25358403, 2014). "Increased ROCK1 expression is also widely observed in pulmonary fibrosis conditions." (PMID 30902967, 2019). "ROCK1 is also believed to contribute to pulmonary fibrosis in animal models." (PMID 30902967, 2019). "Therefore, it is hypothesized that mTOR pathway, ZEB1, and ROCK1 may play a role in the pathogenesis of pulmonary fibrosis." (PMID 25358403, 2014). "In order to determine the changes of TGFβ1/NOX4 and PDGF/ROCK signal pathway in idiopathic pulmonary fibrosis after Yifei decoction combined with MitoQ intervention, we detected the expression levels of TGFβ1, NOX4, PDGFR-β, and ROCK1." (PMID 34135982, 2021).
pulmonary fibrosis (continued). "In lung fibrosis, NOX4/ROS is located upstream of the RhoA/ROCK1 signaling pathway, and the two molecules are oppositely located in renal fibrosis." (PMID 31130857, 2019). "For examples, functional studies are needed to identify the role of mTOR, ROCK1, and ZEB1 in the pathogenesis of pulmonary fibrosis." (PMID 25358403, 2014). "This study demonstrates that ROCK1 and ROCK2 could protect mice from bleomycin pulmonary fibrosis induction." (PMID 34830058, 2021). "In pulmonary fibrosis, NOX4/ROS is an upstream signalling pathway of RhoA/ROCK1." (PMID 32496208, 2020). "Indeed, ROCK1 and ROCK2 have been the target of studies in pulmonary fibrosis." (PMID 34830058, 2021).
bladder cancer (13 papers, 2012 to 2025). "Up-regulation of ROCK1 has been reported in bladder cancer and it has been verified to be associated with the progression of BCa." (PMID 24180482, 2013). "Previous reports have demonstrated the function of microRNAs (eg, microRNA-135a and microRNA124-3p) in ROCK1 regulation in prostate, gastric, and bladder carcinoma." (PMID 25380619, 2014). "Next, to investigate if miR-124-3p exerts its function via ROCK1 on migration and invasion of human bladder cancer cells, we ectopically expressed ROCK1 together with miR-124-3p in T24 cells." (PMID 24180482, 2013). "In our current study, we revealed that ROCK1 was commonly over-expressed in bladder cancer tissues by immunohistochemical staining, comparing with the paired non-tumor tissues (NT)." (PMID 24180482, 2013). "Then wound healing assays and transwell assays were taken to observe the function of ROCK1 in bladder cancer cell migration and invasion." (PMID 24180482, 2013). "To further prove if miR-124-3p represses ROCK1 expression in the human bladder cancer intracellular environment, we analysed the changes of ROCK1 expression in T24, UM-UC-3 and J82 after miR-124-3p overexpression." (PMID 24180482, 2013). "Luciferase reporter assays demonstrated that oncogene ROCK1 is a direct target of miR-1280 in bladder cancer." (PMID 23056431, 2012). "ROCK1 has been reported to be an important molecule that drives bladder cancer migration and invasion." (PMID 23056431, 2012). "We also performed functional analyses to confirm the anti-tumor effects of miR-1280 and show that miR-1280 directly targets oncogene ROCK1, an important molecule in bladder cancer cell migration and invasion." (PMID 23056431, 2012). "Here for the first time we report on the tumor suppressor activity of microRNA-1280 (miR-1280) in bladder cancer and show that it bladder cancer migration and invasion by directly targeting ROCK1." (PMID 23056431, 2012). "Overexpression of ROCK1 has been reported to occur in various cancers and the Rho/ROCK pathway has been found to be associated with progression of bladder cancer." (PMID 23056431, 2012). "Elevated protein expression of the ROCK paralogs has been reported across several cancers including hepatocellular carcinoma, osteosarcoma, and breast, colon, and bladder cancers, and the expression of ROCK1 has been shown to have strong prognostic value in colorectal, breast, and bladder cancer." (PMID 28709411, 2017). "miR-124-3p can repress the migration and invasion of bladder cancer cells via regulating ROCK1." (PMID 24180482, 2013). "As we have revealed the down-regulation of ROCK1, MMP2 and MMP9 in bladder cancer tissues by IHC, we wanted to know whether knocking down miR-124-3p could result in the up-regulation of ROCK1, MMP2 and MMP9." (PMID 24180482, 2013). "Firstly, to investigate whether ROCK1 is upregulated in bladder cancer, we detected its expression level in bladder cancer tissues." (PMID 24180482, 2013). "Subsequently, we demonstrated ROCK1 as direct target of miR-124-3p in human bladder cancer." (PMID 24180482, 2013). "Since ROCK1 is an important molecule that is involved in bladder cancer migration and invasion, we examined whether ROCK1 is a target of miR-1280 in bladder cancer." (PMID 23056431, 2012). "Therefore these results indicate that miR-1280 inhibits migration/invasion and thus metastasis of bladder cancer that is mediated through downregulation of oncogene ROCK1." (PMID 23056431, 2012). "Thus, we considered that ROCK1 is more important in miR-124-3p-Rho/ROCK pathway in bladder cancer." (PMID 24180482, 2013). "Various compounds are currently being used as ROCK1 inhibitors; therefore restoration of tumor suppressor miR-1280 might be therapeutically useful either alone or in combination with these compounds in the treatment of bladder cancer." (PMID 23056431, 2012). "On the other hand, ROCK1-induced high level of c-Met, MMP2 and MMP9, which enhances migration and invasion of bladder cancer cells." (PMID 24180482, 2013).
bladder cancer (continued). "ROCK1, MMP2, MMP9 were up-regulated in bladder cancer tissues." (PMID 24180482, 2013).